SLC7A11 (solute carrier family 7 member 11)
Diseases named in the same sentence as SLC7A11 in open-access papers (continued):
Sharing a sentence is not in itself a finding about the gene and the disease.
epilepsy (11 papers, 2014 to 2025). A brain disorder characterized by episodes of abnormally increased neuronal discharge resulting in transient episodes of sensory or motor neurological dysfunction, or psychic dysfunction. "We conducted qPCR analyses on hippocampal tissue from mice with epilepsy to identify potential proteins regulating the m6A methylation of SLC7A11." (PMID 39310099, 2024). "Scn8a and Slc7a11 are the two most recently identified genes that can modify aspects of epilepsy in Kcna1 KO mice." (PMID 37240170, 2023). "Notably, m6A modifications on SLC7A11 were significantly higher in mice with epilepsy compared with controls." (PMID 39310099, 2024). "Therefore, we investigated whether SLC7A11 in hippocampal astrocytes of mice with epilepsy undergoes m6A modification." (PMID 39310099, 2024). "Further examination of changes in m6A methylation levels, specifically in SLC7A11 mRNA, revealed upregulated m6A methylation modifications in both the CDS region and 3′UTR in the epilepsy group." (PMID 39310099, 2024).
esophageal squamous cell carcinoma (11 papers, 2021 to 2025). Esophageal squamous cell carcinoma (ESCC) is a type of esophageal carcinoma (EC) that can affect any part of the esophagus, but is usually located in the upper or middle third. "They found that lymph node metastases were more common in SLC7A11-positive patients than in SLC7A11-negtive patients, suggesting that SLC7A11 expression is linked to tumor development and metastasis in esophageal squamous cell carcinoma." (PMID 37488128, 2023). "Solute carrier family 7 member 11(SLC7A11) is a component of cysteine/glutamate transporter, which plays a key role in tumor growth; however, its underlying effect on radiosensitivity in esophageal squamous cell carcinoma (ESCC) remains unclear." (PMID 34446045, 2021). "SLC7A11 expression has also been associated with severity and radiosensitivity in tissues of esophageal squamous cell carcinoma (ESCC) patients." (PMID 39335604, 2024). "NRF2, for instance, drives resistance in esophageal squamous cell carcinoma by activating SLC7A11, reducing oxidative stress, and preventing radiation-induced lipid peroxidation." (PMID 39935430, 2025). "For instance, Nrf2-induced SLC7A11 transcription activation promoted radioresistance in esophageal squamous cell carcinoma through inhibiting ferroptosis." (PMID 38887622, 2024). "Li finds that nuclear factor erythroid 2-related factor 2 (NRF2) can inhibit radiation-induced ferroptosis by regulating SLC7A11 in esophageal squamous cell carcinoma (ESCC), promoting radioresistance in ESCC." (PMID 36589232, 2022). "For example, pancreatic cancer and renal cell carcinoma are sensitive to RT, which may be related to their dependence on cystine uptake; inhibition of SLC7A11 and promotion of ferroptosis can increase the radiosensitivity of esophageal squamous cell carcinoma." (PMID 36457125, 2022). "NRF2 upregulates SLC7A11, enhances GSH synthesis, and supports GPX4 activity, driving radio- and chemoresistance in cancers such as esophageal squamous cell carcinoma, clear cell renal cell carcinoma, lung adenocarcinoma, and nasopharyngeal carcinoma." (PMID 39935430, 2025).
fibrosarcoma (11 papers, 2019 to 2025). A malignant mesenchymal fibroblastic neoplasm affecting the soft tissue and bone. "Given the role of SNF2L as a transcription activator, we validated the transcriptional alteration of SLC7A11 in HT-1080 fibrosarcoma cells using transcriptome sequencing." (PMID 39532848, 2024). "Through anion exchange and siRNA adsorption, the resulting multifunctional siRNA@ABMBP-COF, which possesses both the HK2 inhibitor 3-bromopyruvate and SLC7A11 siRNA, exhibits powerful synergistic antitumor activity against fibrosarcoma via the ferroptosis and apoptosis pathways." (PMID 35865896, 2022). "Similarly, knockdown of SLC7A11, a subunit of system Xc to import cystine in the cell, sensitized fibrosarcoma cells to erastin-induced death." (PMID 32760210, 2020). "interestingly, we observed that SLC7A11 was upregulated at both the mRNA and protein levels upon E2F1 overexpression in HT1080 (fibrosarcoma) cells." (PMID 36778475, 2023).
head and neck cancer (11 papers, 2018 to 2024). A primary or metastatic malignant neoplasm affecting the head and neck. "The FDA-approved class I FIN sulfasalazine (SAS) has been shown to induce cell ferroptosis in breast and head and neck cancers by inhibiting SLC7A11, as evidenced by studies." (PMID 38028615, 2023). "Upregulation of SLC7A11, a member of cystine/glutamate antiporter, protected cancer cells from ferroptosis while SLC7A11 inhibition induced ferroptosis and enhanced cisplatin cytotoxicity in cisplatin-resistant head and neck cancer cells." (PMID 35692844, 2022). "It has been shown that the expression of SLC7A11 was upregulated in head and neck cancers, but was lower in HPV positive head and neck cancers compared to HPV negative tumors." (PMID 35328568, 2022). "In this manuscript, we have summarized how these non-coding RNAs are implicated in various aspects of ferroptosis in head and neck cancers including iron metabolism (Mfrn1/2, LOX, TfR1, and LTF), lipid metabolism (LKB1 and ACSL4), and ROS accumulation (SLC3A2, SLC7A11, ATF3, Nrf2, and GPX4)." (PMID 35328568, 2022). "Several microRNAs have been known to modulate SLC7A11 in head and neck cancers." (PMID 35328568, 2022). "In addition to repressing c-myc/HK-II, TPL suppressed NRF2/SLC7A11 axis and led to accumulation of ROS in head and neck cancer cells." (PMID 34108030, 2021). "TPL also suppressed NRF2/SLC7A11 axis and induced ROS accumulation in cancer cells, thus synergized with erastin to kill head and neck cancer cells, regardless of the expression status of GSDME." (PMID 34108030, 2021).
inflammatory bowel disease (11 papers, 2016 to 2025). A spectrum of small and large bowel inflammatory diseases of unknown etiology. "Sulfasalazine (SSZ), an FDA-approved drug for the treatment of rheumatoid arthritis and inflammatory bowel diseases (IBD), is recognized as an xCT (encoded by SLC7A11) inhibitor and therefore acknowledged as a FIN." (PMID 38612455, 2024). "Riluzole, an SLC7A11 inhibitor used to manage ALS (Amyotrophic lateral sclerosis), and sulfasalazine, which is used to treat IBD (inflammatory bowel disease) and arthritis were also identified as potential candidates." (PMID 32899191, 2020). "Of the 5 drugs targeting SLC7A11, riluzole, a noncompetitive metabotropic glutamate receptor 1 (mGluR1) antagonist, and sulfasalazine, a cystine/glutamate antiporter system xc-inhibitor used to treat inflammatory bowel disease and arthritis, have antitumor properties." (PMID 32899191, 2020).
kidney cancer (11 papers, 2016 to 2025). Primary or metastatic malignant neoplasm involving the kidney. "Moreover, SLC7A11-positive macrophages were associated with poor prognosis among kidney cancer patients." (PMID 36470862, 2022). "Studies have shown that high expression of SLC7A11 in kidney cancer cells leads to NADPH depletion under glucose starvation, ultimately triggering disulfidptosis-mediated cell death." (PMID 39865281, 2025). "Subsequently, in vitro experiments were performed to gain deeper insights into the impact of SLC7A11 on kidney cancer cell function." (PMID 38862242, 2024). "In kidney cancer, SLC7A11-positive macrophages were mainly detected in GPNMB positive or FN1 positive macrophage sub-clusters." (PMID 36470862, 2022). "The association of CALU with GPX4, HSPA5 and SLC7A11 in the pan-cancer data revealed a significant relationship between CALU and ferroptosis among various tumors, especially the breast, prostate and kidney cancers where ferroptosis was more commonly observed." (PMID 34150647, 2021). "Kidney cancer patients with SLC7A11-positive myeloid cells had a poor prognosis." (PMID 36470862, 2022). "In order to evaluate the SLC7A11 in other subtypes of kidney cancer, we have used the TCGA data and found that SLC7A11 significant upregulation in RCC subtypes ccRCC, chromophobe RCC (chRCC) and papillary RCC (pRCC) and the upregulation was associated with significant poor survival of patients." (PMID 27144525, 2016).
lymphoma (11 papers, 2014 to 2026). A malignant (clonal) proliferation of B- lymphocytes or T- lymphocytes which involves the lymph nodes, bone marrow and/or extranodal sites. "ATF5, a MYC-regulated transcription factor overexpressed in these lymphomas, induces SLC7A11 expression." (PMID 41998301, 2026). "Targeting SLC7A11 induces apoptosis and tumor regression for KSHV/HIV-associated lymphoma." (PMID 38470932, 2024).
myocardial infarction (11 papers, 2020 to 2026). Gross necrosis of the myocardium, as a result of interruption of the blood supply to the area, as in coronary thrombosis. "In a post-myocardial infarction fibrosis model, SLC7A11 upregulation was accompanied by reduced fibrosis in rats with heart failure." (PMID 40249927, 2025). "Inhibition of MALAT1 can increase theprotein expression level of NRF2/SLC7A11 in myocardial infarction models, bothin vitro and in vivo, while reducing ferrous ion levels andlipid peroxidation in cells." (PMID 39076494, 2024). "Our study also showed upregulated GPX4 and SLC7A11 improved cardiac function and reduced myocardial infarction size in the I/R-MMA + FER-1 group, as compared to the I/R-MMA group." (PMID 38238728, 2024). "In contrast, RSL3, an activator of ferroptosis, reduced GPX4 and SLC7A11 expression, suggestive of ferroptosis activation, which led to a decrease in cardiac function and an increase in the myocardial infarct size." (PMID 38238728, 2024). "In conclusion, miR-432-5p inhibits the ferroptosis in cardiomyocytes induced by H/R by activating Nrf2/SLC7A11 axis by degrading Keap1 and is a potential drug target for clinical myocardial infarction treatment." (PMID 37822721, 2023). "This shows that Nrf2 may regulate SLC7A11 through the same pathway during ischemia, but their regulatory role in myocardial infarction needs further clarified." (PMID 37822721, 2023).
asthma (10 papers, 2021 to 2025). "ICGAC suppresses asthma-associated inflammatory and oxidative stress responses through the upregulation of GPX4, SLC7A11, and Nrf2 in lung tissue." (PMID 40430003, 2025). "One recent study found that Slc7a11 can influence the intracellular (and extracellular) redox imbalance in T2-high asthma by regulating the GSH/GSSG ratio." (PMID 37301835, 2023). "In a previous study, SLC7A11 was identified as a ferroptosis-related gene in airway epithelial cells that predicted asthma exacerbations." (PMID 34257337, 2021). "In the SLC7A11-low group, gene sets were mainly enriched in immune-related signaling pathways, such as viral myocarditis, the intestinal immune network for IgA production, asthma, and allograft rejection." (PMID 37880315, 2023). "In this study, we explored how ICGAC suppresses asthma-related inflammation and oxidative stress, specifically by upregulating GPX4, SLC7A11, and Nrf2 in lung tissues." (PMID 40430003, 2025). "We identified SLC7A11, SLC2A12, ZEB1, ATF3, and HIC1 common between DEGs and TFs involved with asthma and ferroptosis." (PMID 34257337, 2021). "The downregulation of antioxidant proteins (SLC7A11 and GPX4) and the upregulation of toxic derivatives (4-HNE and MDA) shown in the OVA group in this study demonstrates that ferroptosis signaling is involved in OVA-induced asthma pathogenesis." (PMID 36290772, 2022). "Consistently, the expression of SLC7A11, SLC3A2, and GPX-4 was also inhibited, while the level of ALOX5 was enhanced in lung tissues of asthma mice or IL-13-stimulated BEAS-2B cells, further demonstrating the initiation of ferroptosis during the development of asthma." (PMID 35154576, 2022).
clear cell renal cell carcinoma (10 papers, 2021 to 2025). "Analysis of TCGA cohorts showed that high SLC7A11 expression was correlated with an inferior overall survival in renal clear cell carcinoma." (PMID 40688501, 2025). "Similarly, DPP9 disrupts KEAP1‐NRF2 binding through its conserved ESGE motif, leading to NRF2‐dependent transcriptional activation of SLC7A11 and promoting tumorigenesis and drug resistance in renal clear cell carcinoma." (PMID 40583858, 2025). "Moreover, MITD1 deficiency has been discovered to hinder the growth and migration of clear cell renal cell carcinoma by inducing ferroptosis through the TAZ/SLC7A11 pathway." (PMID 38159255, 2023). "Moreover, the knockdown of tribbles pseudokinase 3 triggers ferroptosis via the SLC7A11/GPX4 pathway, enhancing sunitinib efficacy in clear cell renal cell carcinoma." (PMID 39935430, 2025). "Unlike our findings, they found that DPP9 inhibited ferroptosis and induced sorafenib resistance in Clear Cell Renal Cell Carcinoma not by regulating the NRF2 downstream target gene NQO1, but by regulating SLC7A11." (PMID 39094401, 2024).
colon adenocarcinoma (10 papers, 2021 to 2025). "The SLC7A11 expression in colon adenocarcinoma is positively associated with microsatellite instability and immunotherapeutic response." (PMID 36846715, 2023). "SLC7A11, a core target-regulating ferroptosis, is frequently overexpressed in most tumors, such as colon adenocarcinoma (COAD), lung adenocarcinoma (LUAD), and esophageal cancer (ESCA), which would affect lymphatic metastasis, the infiltration of immune cells, etc.." (PMID 37675227, 2023). "We searched TCGA databases, the results indicated that SLC7A11 expression and SLC3A2 expression were obviously enhanced in colon adenocarcinoma (COAD), compared with normal samples." (PMID 41341590, 2025). "However, the mechanism of SLC7A11 in the pathogenesis of colon adenocarcinoma (COAD) is rarely studied in detail." (PMID 35517862, 2022).
Stroke (10 papers, 2021 to 2026). Sudden impairment of blood flow to a part of the brain due to occlusion or rupture of an artery to the brain. "Recently, differential gene expression analysis revealed that four DRGs (SLC2A3, SLC2A14, SLC7A11, and NCKAP1) are associated with stroke." (PMID 40109666, 2025). "XMZS may activate NRF2/GPX4/SLC7A11 pathway to treat stroke by attenuating neuronal ferroptosis and is applicable in clinical management of stroke." (PMID 41822239, 2026). "The data revealed that MGF significantly upregulated the expression of NRF2, GPX4, SLC7A11 and FTL, whereas ML385 inhibited the influence of MGF on these proteins, suggesting that MGF might inhibits ferroptosis in stroke by targeting the NRF2/ARE pathway." (PMID 40474971, 2025). "Therefore, we observed the effects of kaempferol on protein levels of SLC7A11, GPX4, and Nrf2 in an in vitro stroke model of OGD/R." (PMID 34206421, 2021).
atherosclerosis (9 papers, 2021 to 2026). A disease characterized by the build-up of fatty material and calcium deposition in the arterial wall resulting in partial or complete occlusion of the arterial lumen. "Macrophage-targeting lipid nanoparticles loading with ferrostatin-1, an antioxidant reagent, promotes Slc7a11-mediated glutathione synthesis, also enhanced plaque stability and ameliorated the progression of atherosclerosis." (PMID 41777250, 2026). "In ApoE−/− mice, hepcidin-knockdown or SLC7A11-overexpression inhibits plaque macrophage ferroptosis, therefore delaying the progression of atherosclerosis." (PMID 37942067, 2023). "Inhibiting ox-LDL-induced macrophage ferroptosis through reduced Fe2+ overload, lipid peroxidation, or elevated GPX4, FTH1, and SLC7A11 expression may alleviate atherosclerosis." (PMID 37942067, 2023). "Additionally, cigarette tar promoted the progression of atherosclerosis by inducing ferroptosis in macrophages through the NF-κB-activated hepcidin/FPN1/SLC7A11 pathway." (PMID 37760781, 2023). "Thus, it can be concluded that capsiate may mitigate atherosclerosis by modulating ferroptosis through the Nrf2/GPX4/SLC7A11 pathway." (PMID 40029381, 2025). "Collectively, these findings confirm that catechin prevents ox-LDL-induced ferroptosis in VSMCs by activating the Nrf2/SLC7A11/GPX4 pathway, highlighting its potential therapeutic value for atherosclerosis." (PMID 40529424, 2025). "The study further demonstrated that Qingxin Jieyu Granule exerts its inhibitory effects on ferroptosis in vulnerable atherosclerosis plaques, partially mediated by the GPX4/xCT (the cystine/glutamate antiporter SLC7A11) signaling pathway." (PMID 40070365, 2025). "The protective effects of capsiate against atherosclerosis may be mediated through the PI3K/AKT/NF-κB and Nrf2/GPX4/SLC7A11 signaling pathways." (PMID 40029381, 2025). "Although our study links mechanotransduction to vascular inflammation via the Piezo1/BHLHE40/SLC7A11 axis, validation in disease models such as atherosclerosis or other cardiovascular pathologies is lacking." (PMID 41372156, 2025).
leukemia (9 papers, 2021 to 2026). A malignant (clonal) hematologic disorder, involving hematopoietic stem cells and characterized by the presence of primitive or atypical myeloid or lymphoid cells in the bone marrow and the blood. "As anticipated, DFX administration also yielded a significant augmentation in the mRNA levels of genes pertinent to ferroptosis, namely, NRF2, KEAP1, HO-1, GPX4, and SLC7A11, within the leukaemia cells of individuals with ALL." (PMID 38671872, 2024). "LINC00618 expedites ferroptosis through adding lipid reactive oxygen and iron in leukemia and reduces the level of SLC7A11, which accelerates ferroptosis by inducing apoptosis." (PMID 35768833, 2022). "LINC00618 accelerates ferroptosis by increasing the levels of lipid reactive oxygen and iron in leukemia and decreases the expression of SLC7A11, which accelerates ferroptosis by inducing apoptosis." (PMID 34869304, 2021). "LINC00618 was confirmed as accelerant of ferroptosis via reducing the expression of SLC7A11 in leukemia." (PMID 35127813, 2021). "Although the functional consequences of this stratification are not clear in the context of actual ferroptosis induction, we reasoned that decreased GPX4, FTH1 and SLC7A11 levels might facilitate ferroptosis induction in leukemia cells." (PMID 40382332, 2025). "Accordingly, our data revealed that apigenin caused a large induction of ferroptosis in ALL cells, as evidenced by increased levels of peroxidized lipids and Fe2+, as well as reduced levels of SLC7A11 or GPX4, suggesting that ferroptosis might be relevant to the anti-leukemia activity of apigenin." (PMID 39866226, 2025).
ovarian tumor (9 papers, 2021 to 2025). "OTUB1 is an ovarian tumor deubiquitinase family member with reported functions to regulate SLC7A11 stability via direct protein interaction." (PMID 35347117, 2022). "Furthermore, the combination of cisplatin and the SLC7A11 inhibitor HG106 significantly inhibits the growth of ovarian tumors." (PMID 40890129, 2025). "SLC7A11, which is responsible for GSH synthesis and oxidative stress in cells and is highly expressed in ovarian tumor cells, was unchanged in the OVCAR-8 cells, while it was slightly increased in the NCI/ADR-RES cells." (PMID 39201357, 2024). "OTUB1, a DUB of the ovarian tumor (OTU) family, was identified as a SLC7A11-interacting protein which stabilizes SLC7A11 by preventing SLC7A11 from undergoing ubiquitination and proteasomal degradation." (PMID 33000412, 2021).